P4HA2 (prolyl 4-hydroxylase subunit alpha 2)
Diseases named in the same sentence as P4HA2 in open-access papers (continued):
Sharing a sentence is not in itself a finding about the gene and the disease.
tumor (48 papers, 2010 to 2026). "Yes‐associated protein 1 (YAP1) depends on P4HA2 to activate epithelial‐mesenchymal transition (EMT) to make tumor cells metastasize." (PMID 40347062, 2025). "In KRAS mutation group, high P4HA2 expression is the only independent prognostic factor for tumor recurrence, so it can be suggested to be a novel target for therapy." (PMID 38522060, 2024). "In KRAS mutation group, high P4HA2 expression is the only independent prognostic factor in tumor recurrence." (PMID 38522060, 2024). "Further TIMER analysis indicated that the immune system had a good effect on tumor microenvironment, and that the mutations of DARS / GDI2/P4HA2/TRUB1 had important application value in tumor immunology." (PMID 35111402, 2022). "P4HA2 is known to have a major effect on physical properties of tumour‐associated ECM, which in turn leads to increased stiffness during cancer progression." (PMID 31268606, 2019). "P4HA2 is implicated in regulating tumor microenvironment formation and may play roles in inflammation and tumor immunity." (PMID 40406250, 2025). "Moreover, P4HA1 and P4HA2 were associated with tumor stage, patient prognosis, and immune cell infiltration." (PMID 38806556, 2024). "The hub gene-P4HA2 could modulate the LDs accumulation in CC cells and was closely associated with tumor infiltrating cells lymphocytes and immune checkpoint genes." (PMID 34249930, 2021). "Also, there was a positive association between high P4HA2 expression either within tumour epithelial cells or stromal cells and high HIF-1a expression." (PMID 30410060, 2018). "However, further functional studies are highly recommended to understand the underlying mechanisms of P4HA2 expression in carcinogenesis and tumour progression either from the tumour cells or the surrounding stroma." (PMID 30410060, 2018). "The anti‐tumor impact of quercetin may be associated with P4HA2." (PMID 40347062, 2025). "In pan-cancer single-cell transcriptomics, P4HA2 showed higher expression in malignant tumor cells and fibroblasts, with lower expression in B cells and T cells." (PMID 41424847, 2026). "The expression of P4HA2 was significantly higher in the tumor tissues than in the adjacent paracancerous tissues, consistent with the findings from the TCGA, GEO, and HPA databases." (PMID 40379610, 2025). "GABPA-overexpressed cells generated the fewest foci, while P4HA2 overexpression induced 2-fold higher numbers of tumor cell seeding, compared to control J82 cells with an empty vector (J82/vector)." (PMID 40813762, 2025). "Univariate analysis indicated that P4HA2 expression, tumor T stage, and M stage had significant impacts on patient prognosis." (PMID 40406250, 2025). "For example, in COL1A1, COL1A2, COL3A1 and COL5A1 HYP peptides were enriched in the tumor nodule boundaries, a pattern that was lost in P4HA2-depleted tumors." (PMID 40671813, 2025). "We found that the inhibitors of P4H can weaken the function of PTC cells, and P4HA2 expression is closely related to tumor size in patients with PTC, which indicates that P4HA2 is very likely a target for the treatment of PTC." (PMID 40379610, 2025). "P4HA2 can also regulate the expression of tumor-related genes, increase the malignant phenotype of tumor cells, and promote drug resistance." (PMID 40406250, 2025). "The positive cells density (PCD) and the immunohistochemical score (H-Score) for P4HA2 were significantly higher in tumor tissues than in the adjacent paracancerous tissues." (PMID 40379610, 2025). "P4HA2 governs cellular biological functions in certain tumor cells, including cell proliferation and differentiation." (PMID 40347062, 2025). "P4HA2 dysregulation contributes significantly to tumor growth, invasion, and therapeutic resistance." (PMID 40406250, 2025). "In vivo assessments confirmed the tumor-promoting effects of P4HA2, including subcutaneous tumor formation and multiple-organ (lung and liver) metastasis." (PMID 40379610, 2025).
tumor (continued). "Aspirin regulates NF‐κB pathways to inhibit P4HA2 protein activity, preventing collagen deposition and inhibiting tumor growth." (PMID 40347062, 2025). "Overall, our data suggest that P4HA2 plays a crucial role in promoting the tumor phenotype of PTC cells." (PMID 40379610, 2025). "The involvement of proline 4‐hydroxylase II (P4HA2) in collagen synthesis is crucial in the growth of tumor cells." (PMID 40347062, 2025). "Here, we identify prolyl hydroxylase P4HA2 as a key regulator of tumor dormancy through its dual role in collagen proline hydroxylation and mitochondrial function." (PMID 40671813, 2025). "To further assess the in vivo effect of P4HA2 on tumor growth, we implanted P4HA2-knockdown TPC-1 cells into mice and compared their tumor growth with control mice." (PMID 40379610, 2025). "In this study, we identified P4HA2 as a central regulator of tumor dormancy, functioning at the interface of collagen proteostasis, autophagy and mitochondrial metabolism." (PMID 40671813, 2025). "We further validated in vitro that the KynA/P4HA2/HILPDA axis mediates lipid metabolism reprogramming in tumor cells." (PMID 39920992, 2025). "P4HA2 not only regulates the formation of the tumor microenvironment but also potentially plays a role in inflammation and tumor immunity." (PMID 40406250, 2025). "We next performed Gene Ontology and KEGG pathway analyses, which revealed that the differentially expressed proteins were involved in multiple pathways related to tumor proteins regulated by P4HA2." (PMID 40406250, 2025). "In previous studies, P4HA2 altered the tumor microenvironment by influencing collagen structure, function, and stability." (PMID 40406250, 2025). "Together, these findings establish P4HA2 as a critical regulator of tumor cell dormancy, linking its expression to quiescence and its depletion to the reactivation of proliferation and metastatic outgrowth via modulation’of cell cycle regulatory networks." (PMID 40671813, 2025). "Studies have demonstrated that P4HA2 governs the expression of STAT1, which, as a crucial molecule of signal transduction within the tumor microenvironment, is intimately associated with the inflammatory response and tumor immune surveillance." (PMID 40406250, 2025). "Multivariate analysis also shows that age, tumor stage, and high P4HA2 expression are correlated with overall survival." (PMID 38951593, 2024). "Many previous studies demonstrated that increased collagen deposition by P4HA2 offers physical and biochemical signals to enhance tumor initiation and growth." (PMID 38522060, 2024). "Congruently, in vivo orthotopic studies in SCID mice have reported reduced tumor growth, collagen deposition, and lung metastases in P4HA2 knockdown models compared to the controls." (PMID 39716322, 2024). "In summary, this study demonstrates changes affecting HCC cells after exposure to corosolic acid and discloses P4HA2 as a potential target in corosolic acid anti-tumor process." (PMID 37248456, 2023). "Our study also demonstrated a potential relationship between P4HA2 expression and tumor immune cell infiltration since P4HA2 expression showed a positive correlation with the levels of macrophages, neutrophils, B, CD4+, and dendritic cells in the HCC tissues." (PMID 37248456, 2023). "Its expression relates to the tumor infiltration status of multiple immune cells, suggesting P4HA2 has a decisive role in how patients with HCC respond to immunotherapy." (PMID 37248456, 2023). "This study found that P4HA2 is a potential target of corosolic acid and part of its anti-tumor mechanism." (PMID 37248456, 2023). "Further, the authors analyzed the relationship between P4HA2 expression and tumor-infiltrating immune cells." (PMID 36403427, 2022). "In the present study, the authors found that P4HA2 is highly expressed in LUAD tumor cells and was a valuable prognostic indicator for LUAD, especially for the BM subtype." (PMID 36403427, 2022).
tumor (continued). "P4HA2 is highly expressed in LUAD tumor cells, especially for the BM subtype, and is a valuable prognostic indicator of LUAD." (PMID 36403427, 2022). "In the present study, the authors found that P4HA2 was highly expressed in LUAD tumor cells, especially in LUAD BM, based on single-cell analysis and in situ detection." (PMID 36403427, 2022). "Under hypoxic tumor conditions, HIF-1 induces expression of genes that encodes collagen prolyl (P4HA1 and P4HA2) and lysyl (PLOD2) hydroxylases." (PMID 34249670, 2021). "Consistent with in vitro data, IHC staining showed weaker Vimentin and N-cadherin expression but stronger E-cadherin expression in tumor tissues from the P4HA2-silenced group than in those from the control group." (PMID 32226497, 2020). "SiHa cells with stable knockdown of P4HA2 were subcutaneously implanted into nude mice, and tumor formation and growth were monitored." (PMID 32226497, 2020). "P4HA2 is a key protein in collagen biosynthesis and plays a crucial role in promoting various tumor progressions." (PMID 32226497, 2020). "IHC staining showed that the relative P4HA2 staining was remarkably weaker in the tumor tissues from P4HA2 knockdown group." (PMID 32226497, 2020). "Taken together, our data indicate that YAP1 drives P4HA2 expression in RASSF1A‐methylated tumours, resulting in increased organization of collagen and elevated stiffness of the tumour microenvironment." (PMID 31268606, 2019). "Our data suggest that deregulation of P4HA2 levels in RASSF1‐methylated tumours is a key factor behind the poor prognostic value of these cancers." (PMID 31268606, 2019). "As a result of increased P4HA2 levels in tumour cells, we find increased collagen deposition and ECM stiffness, which supports the appearance of cancer stem‐like cells." (PMID 31268606, 2019). "Immunohistochemical (IHC) staining of P4HA2 levels shows its increased expression in mouse primary tumours (peri‐nuclear localization due to processing of collagen in the ER; Human Protein Atlas), generated by H1299control cells." (PMID 31268606, 2019). "Within the pure DCIS cohort, high P4HA2 expression was observed in 247/481 (51.4%) and 121/481 (25.2%) in tumour epithelial and surrounding stromal cells; respectively." (PMID 30410060, 2018). "When present, P4HA2 was expressed in the cytoplasm of the epithelial tumour cells and surrounding fibroblasts." (PMID 30410060, 2018). "In our study, we evaluated the pattern of P4HA2 expression either within tumour epithelial cells or surrounding fibroblasts in a large annotated cohort of DCIS with long term follow up data." (PMID 30410060, 2018). "Higher P4HA2 expression was observed in mixed DCIS cases compared to pure DCIS both in tumour cells and in stroma." (PMID 30410060, 2018). "In addition, the key gene P4HA2 in the hypoxia signature has been demonstrated to be involved in the regulation of malignant phenotypes of tumor cells and the regulation of HIF-1α stability." (PMID 41559646, 2026). "Studies have found that P4HA2 is also vital in tumor drug resistance." (PMID 40347062, 2025). "Additionally, the number of P4HA2-positive cells was significantly higher in the tumor tissues than in the paracancerous tissue, suggesting the potential role of P4HA2 in the PTC progression." (PMID 40379610, 2025). "The spatial localization of HYP peptides for COL1A1, COL1A2, COL5A1 and COL3A1 exhibited distinct region-specific patterns in dormant D-HEp3 compared to awakened P4HA2-depleted D-HEp3 cells, suggesting differential regulation of collagen hydroxylation across tumor zones." (PMID 40671813, 2025). "Additionally, P4HA2 is a crucial enzyme in collagen synthesis that can promote collagen expression and deposition, leading to tumor growth and metastasis." (PMID 40347062, 2025). "Knocking out tumor cells P4HA2 results in cell apoptosis and growth restriction." (PMID 40347062, 2025). "The tumor formation rate of P4HA2-knockdown TPC-1 cells was significantly lower, at 40%." (PMID 40379610, 2025).
tumor (continued). "To determine the impact of 4HYP-modified collagen matrix produced by P4HA2-depleted cells on tumor cell quiescence, we generated decellularized matrix scaffolds from D-HEp3 nodules or P4HA2-depleted D-HEp3 awakened tumors and seeded D-HEp3 cells expressing a CDK2 biosensor onto them." (PMID 40671813, 2025). "P4HA2 has played a pivotal role in the growth of tumor cells." (PMID 40347062, 2025). "The tumor volume of the sh-P4HA2 group was notably smaller than that of the sh-GFP group." (PMID 38951593, 2024). "Consistent with this, our IHC analysis of breast subcutaneous tumor tissues shows the expression of P4HA2 and PLOD2 in tissue derived from cells overexpressing RASSF1A is less pronounced compared to tissues derived from cells overexpressing RASSF1C and the vector backbone." (PMID 36826019, 2023). "Recently, P4HA2 has been demonstrated to play important roles in tumor, but its function in cancers might be different." (PMID 36998462, 2023). "•P4HA2 is highly expressed in LUAD tumor cells, especially for the BM subtype." (PMID 36403427, 2022). "The authors assessed P4HA2 expression in the LUAD tumor ecosystem using single-cell analysis." (PMID 36403427, 2022). "Interestingly, HIF-1α is involved in the regulation of P4HA1 and P4HA2 expression in tumor cells and fibroblasts." (PMID 36140753, 2022). "Collectively, P4HA2 acts as a tumor promoter in most cancer types." (PMID 34249930, 2021). "The cancer gene expression database analysis showed that the expressions of vesicle regulator P4HA2 were increased in seven out of 33 tumor types compared with controls; and the expression of vesicle regulator AASS in seven out of 33 tumor types was decreased compared with that of controls." (PMID 34368262, 2021). "Furthermore, xenograft tumor mouse model experiment showed silencing P4HA2 significantly inhibited tumor growth in vivo." (PMID 32226497, 2020). "Analysis of genomic instability-related gene sets in pan-cancer transcriptomics revealed positive correlation between P4HA2 and aneuploidy, homologous recombination deficiency, tumor ploidy, single nucleotide variant neoantigens, non-silent mutation rate, and silent mutation rate in BRCA." (PMID 41424847, 2026). "Finally, a significant positive correlation was noted between tumor volume and the number of cells positive for P4HA2 (R = 0.4089, P < 0.01), further corroborating the hypothesis that P4HA2 may play a role in the PTC aggressiveness." (PMID 40379610, 2025). "In patients with HNSC, P4HA1 expression was associated with tumor stage, while P4HA2-3 was not." (PMID 38806556, 2024). "The authors also found that P4HA2 was predominantly involved in several biological functions, e.g., canonical glycolysis, extrinsic apoptotic signaling, NF-kappa B signaling, and response to hypoxia, which are vital biological processes promoting metastasis of tumor cells." (PMID 36403427, 2022). "Therefore, targeting P4HA2 may be an important new strategy of eradicating resistance of cancer stem cells during conventional tumour therapy." (PMID 31268606, 2019). "In mice, tumors formed from P4HA2-depleted D-HEp3 cells exhibited higher levels of PHH3, an increased tumor volume and a shorter latency period when compared with control (Fig. Supp." (PMID 40671813, 2025). "The tumor number in lungs derived from J82 cells overexpressing both GABPA and P4HA2 was almost the same as that of J82/vector cells." (PMID 40813762, 2025). "Our findings reveal P4HA2 promotes CRC progression and suppresses anti-tumor immunity via STAT1/PD-L1 axis regulation." (PMID 40406250, 2025). "In summary, this study indicates that P4HA2 is highly expressed in OSCC tissues, and its expression level correlates with tumor stage, grade, degree of differentiation, lymph node metastasis, and survival time in OSCC patients." (PMID 38951593, 2024). "Compared with normal controls, the expression levels of P4HA1, P4HA2, and P4HA3 were significantly higher in tumor tissues, particularly in HNSC." (PMID 38806556, 2024).
tumor (continued). "Since P4HA2 and SLUG are important regulators of EMT, we can suggest that their higher expression is correlated with higher tumor budding." (PMID 38522060, 2024). "Immunofluorescence analysis of tumors isolated from wildtype mice confirmed co-localization of P4HA2 and α-SMA, a fibroblast marker, which is similar with DLBCL tumor samples." (PMID 38909089, 2024). "P4HA2 expression was significantly enhanced in HNSCC, and its overexpression was correlated to tumor aggressiveness and a poor prognosis in patients." (PMID 38777998, 2024). "We injected sh-P4HA2 and sh-GFP cells into the BALB/c nude mice for subcutaneous tumor formation to further explore the role of P4HA2 in OSCC growth." (PMID 38951593, 2024). "According to IHC results, a strong immune signal for P4HA2 was observed in the cytoplasm of fibroblasts and LUAD tumor cells." (PMID 36403427, 2022). "Then RNA was extracted from tumor tissue, and qRT-PCR showed that the expression of NEAT1, IL-34, VEGFA, SPINK1, S100A14, and P4HA2 was downregulated and the expression of CCNE2 was upregulated in NEAT1 knockdown tumor tissue." (PMID 36213831, 2022). "Thus, we reasoned that P4HA2 might inhibit CC metastasis through regulating tumor immune escape." (PMID 34249930, 2021). "HIF-1 facilitates ECM remodeling through upregulating expression of P4HA1, P4HA2, and PLOD2 in hypoxic fibroblasts, which results in tumor invasion and metastasis." (PMID 33299876, 2020). "Previous research reported increased levels of P4HA2 and P4HA1 (the two isomers of collagen prolyl 4-hydroxylase) in several types of human cancers and that both enzymes promoted glycolysis in tumor cells." (PMID 33194424, 2020). "In ALDH+CD24-CD44+ BCSCs, we identified P4HA2, PTGR1 and RAB40B as potential prognostic markers, which were virtually related to the status of BCSCs and tumor growth in TNBC cells." (PMID 29471829, 2018). "Although the exact mechanism of how P4HA2 overexpression and subsequent ECM remodelling helps in tumour progression is unclear, there are many hints from existing data." (PMID 30410060, 2018). "Silencing P4HA2 or treatment with the P4HA inhibitor attenuates cell proliferation and suppresses aggressive 3D phenotypes, tumor growth, and cancer metastasis, which are accompanied by reduced collagen deposition." (PMID 24383403, 2014). "Mechanistically, GABPA inhibits P4HA2 expression, thereby reducing collagen cross-linking, whereas GABPA downregulation promotes ECM remodeling, increases tumor stiffness, and results in the acquisition of invasive phenotypes via the mechanotransduction pathway." (PMID 40813762, 2025). "P4HA2 and PLOD2 are regulated by FOXA1, tumor growth factor-β (TGF-β), and hypoxia-inducible factor-α (HIF-1 α) to induce remodeling of extracellular matrix (ECM) and cancer cell stemness to drive tumor cell invasion and metastasis." (PMID 36826019, 2023). "Moreover, P4HA2 expression was positively related to the expression of Ki67 and PCNA, two neoplasm proliferation markers." (PMID 32226497, 2020). "The proportion of cases with high P4HA2 was greater in DCIS-mixed than pure DCIS, both within the tumour epithelial cells (54% of pure DCIS cases vs. 64% of DCIS mixed with IBC, χ2 = 8.6, p = 0.003) and stromal cells (25% for pure DCIS vs. 50% of DCIS mixed with invasion, χ2 = 39.3, p < 0.0001)." (PMID 30410060, 2018). "P4HA2 may also be a valuable prognostic indicator, particularly in the ER + /HER2− luminal tumours for which a biomarker that could prevent over treatment, i.e. avoid radiotherapy, is urgently required." (PMID 30410060, 2018). "Based on the cellular experiments, GABPA inhibits P4HA2 expression, thereby resulting in reduced Col I and III formation and maturation, and we thus sought to assess whether these effects contributed to altered tumor ECM stiffness." (PMID 40813762, 2025).